TUBB1 (tubulin beta 1 class VI)
Description:
Tubulin is the major constituent of microtubules, a cylinder consisting of laterally associated linear protofilaments composed of alpha- and beta-tubulin heterodimers. Microtubules grow by the addition of GTP-tubulin dimers to the microtubule end, where a stabilizing cap forms. Below the cap, tubulin dimers are in GDP-bound state, owing to GTPase activity of alpha-tubulin.
Synonyms: dJ543J19.4; MACTHC1
Tractability: Small molecule: an approved drug acts on it; a high-quality ligand is known; it belongs to a druggable protein family. PROTAC: ubiquitination databases record sites on it; its protein half-life has been measured; a small molecule that binds it is known. Other modalities: an approved drug acts on it.
Target class: Structural protein
Gene: Protein-coding gene on chromosome 20 (59,019,429 to 59,026,654, forward strand). Ensembl gene ENSG00000101162.
Subcellular location: Cytoplasm, cytoskeleton
Subcellular location (Human Protein Atlas): Microtubules; Basal body; Cytokinetic bridge; End piece; Flagellar centriole; Mitotic spindle; Primary cilium; Primary cilium tip; Principal piece
Pathways (Reactome):
Cell Cycle: EML4 and NUDC in mitotic spindle formation; Mitotic Prometaphase; Recruitment of NuMA to mitotic centrosomes; Resolution of Sister Chromatid Cohesion; Sealing of the nuclear envelope (NE) by ESCRT-III; Separation of Sister Chromatids; The role of GTSE1 in G2/M progression after G2 checkpoint
Vesicle-mediated transport: COPI-dependent Golgi-to-ER retrograde traffic; COPI-independent Golgi-to-ER retrograde traffic; COPI-mediated anterograde transport; Gap junction assembly; Microtubule-dependent trafficking of connexons from Golgi to the plasma membrane; Translocation of SLC2A4 (GLUT4) to the plasma membrane
Metabolism of proteins: Carboxyterminal post-translational modifications of tubulin; Formation of tubulin folding intermediates by CCT/TriC; Post-chaperonin tubulin folding pathway; Prefoldin mediated transfer of substrate to CCT/TriC
Signal Transduction: Hedgehog 'off' state; RHO GTPases Activate Formins; RHO GTPases activate IQGAPs
Immune System: MHC class II antigen presentation; PKR-mediated signaling
Neuronal System: Activation of AMPK downstream of NMDARs; Assembly and cell surface presentation of NMDA receptors
Organelle biogenesis and maintenance: Cargo trafficking to the periciliary membrane; Intraflagellar transport
Autophagy: Aggrephagy
Cellular responses to stimuli: HSP90 chaperone cycle for steroid hormone receptors (SHR) in the presence of ligand
Developmental Biology: Recycling pathway of L1
Disease: HCMV Early Events
Hemostasis: Kinesins
Gene Ontology:
Molecular function: GTP binding; structural constituent of cytoskeleton; GTPase activity
Biological process: mitotic cell cycle; microtubule polymerization; microtubule-based process; platelet aggregation; platelet formation; thyroid gland development; thyroid hormone transport
Cellular component: ciliary tip; cilium; cytoplasm; extracellular exosome; intercellular bridge; microtubule cytoskeleton; mitotic spindle; sperm end piece; sperm principal piece; cytoskeleton; microtubule
Genetic constraint (gnomAD): Loss-of-function variants: 32 observed, 27.06 expected, observed/expected ratio (o/e) 1.18, 90% interval 0.89 to 1.59. The upper end of that interval is the gene's LOEUF score, 1.59, which puts it in group 6 of 6, group 1 being the genes least tolerant of losing a copy. Missense variants: 577 observed, 637.74 expected, observed/expected ratio (o/e) 0.9, 90% interval 0.84 to 0.97. Synonymous variants: 226 observed, 251.17 expected, observed/expected ratio (o/e) 0.9, 90% interval 0.81 to 1.
Gene-disease validity (ClinGen):
ClinGen rates the evidence that TUBB1 causes each of these diseases.
macrothrombocytopenia, isolated, 1, autosomal dominant (autosomal dominant): Definitive.
Homologues: Orthologues: chimpanzee TUBB1 (99% identical), macaque TUBB1 (98% identical), guinea pig TUBB1 (92% identical), mouse Tubb1 (92% identical), rabbit TUBB1 (92% identical), rat Tubb1 (91% identical), pig TUBB1 (88% identical), dog TUBB1 (82% identical), tropical clawed frog tubb1 (79% identical), zebrafish tubb1 (78% identical). Paralogues in human: TUBB2B (79% identical), TUBB2A (78% identical), TUBB4B (78% identical), TUBB4A (78% identical), TUBB (78% identical), TUBB3 (78% identical), TUBB6 (77% identical), TUBB8 (76% identical), TUBB8B (74% identical), TUBA1B (42% identical), TUBA4A (42% identical), TUBA1A (41% identical), and 11 more.